CYP4Z1 (cytochrome P450 family 4 subfamily Z member 1)
Description:
A cytochrome P450 monooxygenase that catalyzes the in-chain oxidation of fatty acids. Catalyzes the hydroxylation of carbon-hydrogen bonds. Hydroxylates lauric and myristic acids predominantly at the omega-4 and omega-2 positions, respectively. Catalyzes the epoxidation of double bonds of polyunsaturated fatty acids (PUFA). Displays an absolute stereoselectivity in the epoxidation of arachidonic acid producing the 14(S),15(R)-epoxyeicosatrienoic acid (EET) enantiomer. Mechanistically, uses molecular oxygen inserting one oxygen atom into a substrate, and reducing the second into a water molecule, with two electrons provided by NADPH via cytochrome P450 reductase (CPR; NADPH-ferrihemoprotein reductase).
Synonyms: CYP4A20
Tractability: Small molecule: a high-quality ligand is known; it belongs to a druggable protein family. Antibody: UniProt predicts a signal peptide or a membrane-spanning region. PROTAC: ubiquitination databases record sites on it; a small molecule that binds it is known.
Target class: Enzyme; Oxidoreductase
Gene: Protein-coding gene on chromosome 1 (47,067,231 to 47,118,318, forward strand). Ensembl gene ENSG00000186160.
Subcellular location: Endoplasmic reticulum membrane; Microsome membrane
Gene Ontology:
Molecular function: arachidonate 14,15-epoxygenase activity; fatty acid in-chain hydroxylase activity; oxidoreductase activity, acting on paired donors, with incorporation or reduction of molecular oxygen, reduced flavin or flavoprotein as one donor, and incorporation of one atom of oxygen; fatty acid omega-1 hydroxylase activity; heme binding; iron ion binding; monooxygenase activity; oxidoreductase activity, acting on paired donors, with incorporation or reduction of molecular oxygen
Biological process: arachidonate metabolic process; lauric acid metabolic process
Cellular component: endoplasmic reticulum membrane
Genetic constraint (gnomAD): Loss-of-function variants: 33 observed, 42.63 expected, observed/expected ratio (o/e) 0.77, 90% interval 0.59 to 1.03. The upper end of that interval is the gene's LOEUF score, 1.03, which puts it in group 4 of 6, group 1 being the genes least tolerant of losing a copy. Missense variants: 414 observed, 483.55 expected, observed/expected ratio (o/e) 0.86, 90% interval 0.79 to 0.93. Synonymous variants: 134 observed, 164.52 expected, observed/expected ratio (o/e) 0.81, 90% interval 0.71 to 0.94.
Homologues: Orthologues: chimpanzee CYP4Z1 (68% identical), tropical clawed frog cyp4b1.2 (50% identical), tropical clawed frog XB5810926 (50% identical), tropical clawed frog cyp4b1.5 (48% identical), zebrafish cyp4t8 (40% identical), Drosophila melanogaster Cyp4d1 (30% identical), Caenorhabditis elegans cyp-31A2 (30% identical), Caenorhabditis elegans cyp-31A3 (30% identical), Drosophila melanogaster Cyp4c3 (30% identical), Drosophila melanogaster Cyp312a1 (30% identical), Drosophila melanogaster Cyp4d2 (30% identical), Drosophila melanogaster Cyp4s3 (29% identical), and 22 more. Paralogues in human: CYP4X1 (54% identical), CYP4A11 (51% identical), CYP4A22 (50% identical), CYP4B1 (44% identical), CYP4F2 (39% identical), CYP4F11 (38% identical), CYP4F3 (38% identical), CYP4F8 (38% identical), CYP4F12 (37% identical), CYP4F22 (37% identical), CYP4V2 (32% identical), CYP19A1 (19% identical).
Diseases named in the same sentence as CYP4Z1 in open-access papers:
CYP4Z1 is named in the same sentence as 36 diseases in open-access papers, as found by Europe PMC text mining. Sharing a sentence is not in itself a finding about the gene and the disease. The quoted sentences say what the papers report.
breast carcinoma (32 papers, 2010 to 2026). "For example, CYP4Z1 was found to be frequently upregulated in primary mammary carcinoma and ovarian cancer, and it was associated with tumor progression and metastasis." (PMID 41020804, 2025). "Thirteen TAAs were derived from CYP4Z1, which is implicated in many cancer types and elicits autoantibodies in breast cancer patients." (PMID 37906288, 2024). "For example, PDO207P#C4 ClustGS included the mesenchymal marker VIM and CYP4Z1, which are associated with poor prognosis and high-grade tumors in breast cancer." (PMID 36810117, 2023). "This aberrant cell surface localisation enhances the development of CYP4Z1 autoantibodies in breast cancer patients’ sera and is proposed as a diagnostic biomarker for breast cancer." (PMID 34590601, 2021). "Orphan cytochrome CYP4Z1 is also known as a breast cancer-associated cytochrome due to its putative role in breast cancer through the formation of a signaling molecule 20-hydroxyeicosatetraenoic acid (20-HETE)." (PMID 33809117, 2021). "CYP4Z1 facilitates breast cancer development by induction of ERα expression; thus, its inhibition may have a double effect, eliminating the major breast cancer risk factor." (PMID 40807256, 2025). "CYP4Z2P pseudogene derived from CYP4Z1 (cytochrome P450 family 4 subfamily Z member 1) has been implicated in breast cancer progression by sponging miR-125a, miR-197, miR-204, miR-211, and miR-1226 from CYP4Z1, resulting in enhanced tumor angiogenesis, tamoxifen resistance, and reduced apoptosis." (PMID 29702599, 2018). "The data we present are consistent with previous reports and suggest that CYP4Z1 may be associated with the breast cancer health disparity among the three ethnicities." (PMID 28684774, 2017). "This study establishes Fluvastatin as a novel CYP4Z1-targeted therapeutic candidate for breast cancer, providing preclinical validation for its potential use in combination therapies." (PMID 41526697, 2026). "This study aimed to identify FDA-approved CYP4Z1 inhibitors with anti-breast cancer activity through a drug repurposing strategy, thereby providing preclinical evidence for potential clinical adjuvant therapies." (PMID 41526697, 2026). "Functional studies have demonstrated that CYP4Z1 overexpression promotes tumor angiogenesis in breast cancer through the regulation of VEGF-A and TIMP-2 expression, potentially mediated by PI3K and ERK1/2 activation." (PMID 39958347, 2025). "Of particular interest is CYP4Z1, which seems to be specific for breast cancer, including triple-negative breast cancer (TNBC)." (PMID 41020804, 2025). "Designing suitable small molecules as potential drugs or chemopreventive agents requires understanding of the metabolic role of CYP4Z1 in breast cancer progression and identification of its substrates." (PMID 41020804, 2025). "Some experimental data, including an analysis of the Human Protein Atlas for CYP4Z1 expression in normal and cancer tissues, confirm that CYP4Z1 is mainly localized in the breast and that its activity is significantly increased in breast cancer." (PMID 41020804, 2025). "The CYP4Z1 isoform has triggered particular interest because of its hypothetical role in breast cancer through the formation of the signaling molecule 20-hydroxyeicosatetraenoic acid (20-HETE)." (PMID 41020804, 2025). "In the most extensively investigated ER(+) MCF7 breast cancer cell line, the expression of three orphan CYPs, namely CYP4Z1, CYP2S1, and CYP2W1, was confirmed by several authors." (PMID 41020804, 2025). "By using in vitro and in vivo models, CYP4Z1 overexpression was found to promote breast cancer-cell invasion, migration, proliferation, and tumour angiogenesis." (PMID 34590601, 2021). "Of interest is the finding that the cell surface of breast cancer has shown an abnormal translocation of CYP4Z1 expression compared to nothing displayed on the surface of normal breast cells." (PMID 34590601, 2021).
breast carcinoma (continued). "CYP4Z1 was conditionally overexpressed in breast cancer cells when treated with glucocorticoids and progesterone." (PMID 34590601, 2021). "CYP4Z1 selective expression in breast cancer has inspired researchers to characterise its expression in other cancer types and question its effect on cancer development." (PMID 34590601, 2021). "Stable expression of CYP4Z1 in breast cancer cells has been shown to enhance angiogenesis and tumour growth in vivo by activating PI3K/Akt and ERK1/2 signaling pathways." (PMID 33809117, 2021). "By focusing on breast cancer, we also demonstrate for the first time the significant relationships between CYP4Z1 unique expression and clinicopathological features, as well as identify the key molecules involved in breast cancer pathogenesis." (PMID 33144882, 2020). "Their role as prognostic factors in breast cancer is well documented, but the significance of CYP4Z1 is still unclear." (PMID 33144882, 2020). "The CYP4Z1 positivity rate was more than 80% in HER2-positive patients, indicating that CYP4Z1 plays an important role in the clinical prognosis of breast cancer." (PMID 33144882, 2020). "As a tumour model for CYP4Z1 expression, a panel of different breast cancers was evaluated for CYP4Z1 expression and its relation to histopathological features and prognostic immunohistochemical markers." (PMID 33144882, 2020). "CYP4Z1 expression was shown to be highly induced in breast cancer cells by treatment with dexamethasone or progesterone." (PMID 33144882, 2020). "This was consistent with previous studies showing selective expression of CYP4Z1 in mammary glands and breast cancers." (PMID 33144882, 2020). "This CYP4Z1 expression was translocated to the plasma membrane of breast cancer cells, while nothing displayed on the surface of normal breast cells." (PMID 33144882, 2020). "CYP4Z2P and CYP4Z1 promoted angiogenesis of breast cancer by commonly targeting miR-211, miR-197, miR-1226, miR-125a, and miR-204." (PMID 32185172, 2020). "The ceRNA network of CYP4Z2P and its parental gene CYP4Z1 exerted an anti-apoptotic function in breast cancer." (PMID 32185172, 2020). "In in vivo models, the investigators also showed CYP4Z1 overexpression resulted in increased tumor size, weight, and vascularization, indicating a role for CYP4Z1 in breast cancer tumor growth and progression." (PMID 32581794, 2020). "(E and F) The mRNA and protein expression of stemness markers (ALDH1, SOX2, OCT4, and Nanog) in cells described in A and B. (G) Pearson correlation analysis of the expression of CYP4Z1 and Nanog in basal-like breast cancer (n = 252, P < 0.01)." (PMID 30832689, 2019). "Involvement of CYP4Z1 in breast cancer has been suggested, as it was identified in breast tissue and upregulated in breast carcinoma." (PMID 31480463, 2019). "Increased CYP4Z2P- along with the functional CYP4Z1-3'UTR expression has been shown to promote tumor angiogenesis in breast cancer partly via miRNA-dependent activation of PI3K/Akt and ERK1/2." (PMID 28403188, 2017). "Expression of CYP4Z1 in normal breast tissue was lower than in breast tumor tissue; among the three ethnic groups, AS breast cancer displays the lowest expression of this gene." (PMID 28684774, 2017). "We observed over-expression of LIMCH1, a gene encoding zinc-binding protein, and also four genes encoding iron-binding proteins (LTF, SLC40A1, CYP4Z1 and CYP4Z2P) previously linked to breast cancer." (PMID 21209903, 2010). "They concluded that overexpression of CYP4Z1 and/or 4Z2P might enhance the transcriptional ERα activity, apoptosis, stemness, and resistance to tamoxifen of breast cancer cells." (PMID 41020804, 2025). "Moreover, stable overexpression of CYP4Z1 in breast cancer cells has been reported to promote angiogenesis and tumor growth in mice." (PMID 41020804, 2025). "A stable expression of CYP4Z1 was achieved in BT-474 human HER(+) breast cancer cells." (PMID 41020804, 2025).
breast carcinoma (continued). "Therefore, modulating CYP4Z1 activity appears to be a promising target, even a potential ‘silver bullet’, for breast cancer treatment." (PMID 41020804, 2025). "However, despite attempts, no fruitful results have been obtained so far that would allow the use of CYP4Z1 activity to activate anti-breast-cancer prodrugs." (PMID 41020804, 2025). "Current data suggest that inhibiting CYP4Z1′s breast-specific expression could slow down the growth, progression, angiogenesis, and invasiveness of breast cancer." (PMID 41020804, 2025). "The currently available data indicate that inhibition of CYP4Z1 breast-specific expression may reduce the growth, progression, angiogenesis, and invasiveness of breast cancer." (PMID 40807256, 2025). "Since CYP4Z1 promotes breast cancer development by inducing ERα expression, its inhibition might have a dual benefit by removing a major risk factor for breast cancer." (PMID 41020804, 2025). "In breast cancer, CYP4Z1 activated tumor angiogenesis and growth through the PI3K/AKT pathway." (PMID 39227068, 2024). "Furthermore, it was revealed that expression of CYP4Z1 promoted breast cancer cells’ stemness and resistance to tamoxifen." (PMID 36143940, 2022). "As few functional studies have interrogated the role of CYP4Z1 in cancer development particularly breast cancer, mechanisms behind functions of CYP4Z1 in cervical cancer progression are still unknown." (PMID 34590601, 2021). "Interestingly, treatment of these breast cancer cells with a steroid-receptor blocker, mifepristone, reduced CYP4Z1 conditional overexpression." (PMID 34590601, 2021). "CYP4Z1 is mainly distributed in human liver, kidney, skeletal muscle, testis, and mammary, and is highly expressed in breast cancer, and a regulator of tumor angiogenesis and growth of breast cancer." (PMID 34594219, 2021). "Of specific interest is the aberrant expression of CYP4Z1 in breast cancer." (PMID 34590601, 2021). "Unlike other human CYPs, CYP4Z1 is highly expressed in human breast carcinoma and is associated with poor prognosis." (PMID 33144882, 2020). "CYP4Z1 is an interesting isoform overexpressed in breast cancer." (PMID 32581794, 2020). "In breast cancer, CYP4Z1 3ʹUTR represses migration and EMT by sponging miR-9." (PMID 32066878, 2020). "In breast cancers, CYP4Z1 was expressed in 82% of the cases." (PMID 33144882, 2020). "Additionally, CYP4Z1 overexpression enhanced tumour angiogenesis, growth and spread of breast cancer cells in both in vitro and in vivo models." (PMID 33144882, 2020). "CYP4Z2P, an oncogenic pseudogene of CYP4Z1, has been widely investigated in breast cancer." (PMID 32185172, 2020). "Further studies are therefore required to delineate the role CYP4Z1 plays in breast cancer, specifically identifying the metabolite responsible for inducing growth and angiogenesis, as well as how HET0016 is able to mitigate the effects of CYP4Z1 overexpression." (PMID 32581794, 2020). "We then determined whether the overexpression of CYP4Z1- or CYP4Z2P-3′UTR conferred stemness upon breast cancer cells in vitro." (PMID 30832689, 2019). "CYP4Z1 is expressed in mammary tissue and upregulated in breast cancer tissue." (PMID 31480463, 2019). "Moreover, expression of top five genes (NCEH1, RARRES3, NTN4, CFB and CYP4Z1) that are frequently co-expressed with TNFSF10 in breast cancer patients, have been detected upon transfection with miR-7641 mimic." (PMID 28827731, 2017). "Finally, developing CYP4Z1 antibodies on the surface of breast cancer cells could aid in creating effective immunotherapies, such as anticancer vaccines." (PMID 41020804, 2025). "Moreover, the expression was abnormally localized to the cell surface of breast cancer cells and led to the production of CYP4Z1 autoantibodies that may serve as a biomarker for breast cancer progression." (PMID 33692504, 2021).
breast carcinoma (continued). "Secondly, this study aims to characterise CYP4Z1 expression in different types of breast cancer and to explore the relationship between the expression of CYP4Z1 and histopathological features, as well as key prognostic immunohistochemical markers used for breast cancers." (PMID 33144882, 2020). "It was reported that breast cancer cells exhibited the abnormal translocation of CYP4Z1 protein to the plasma membrane instead of targeting to the intracellular membrane of the endoplasmic reticulum, which caused the CYP4Z1 autoantibody production that might serve as a biomarker for the diagnosis." (PMID 31480463, 2019). "Additionally, we detected whether the six2-mediated promotion of breast cancer cell stemness occurs through the downstream effectors of the ceRNA network between CYP4Z1 and the pseudogene CYP4Z2P and the hTERT/PI3K/Akt and ERK1/2 pathways." (PMID 30832689, 2019). "Both these enzymes are overexpressed in breast cancer, with CYP4Z2P having a similar expression pattern to CYP4Z1 but at a generally lower level which is likely due to the degraded non-functional protein product." (PMID 33809117, 2021). "CYP4Z1 and its transcribed pseudogene CYP4Z2P (96% identity) were initially cloned from SKBr3 breast cancer cells." (PMID 33809117, 2021). "The investigators demonstrated that CYP4Z1 promotes overexpression of the pro-angiogenic factor VEGF-A and the suppression of TIMP-2 (a tumor suppressor) in breast cancer cell lines." (PMID 32581794, 2020). "Transcriptional factor six2, CYP4Z1-3′UTR, and CYP4Z2P-3′UTR were stably overexpressed or knocked down in breast cancer cells via lentivirus infection." (PMID 30832689, 2019). "The expression of CYP4Z1 and the pseudogene CYP4Z2P has been shown to be specifically increased in breast cancer by our group and others." (PMID 30832689, 2019). "CYP4Z1 and its pseudogene CYP4Z2P are two members of cytochrome P450 family 4 which have been found to be over-expressed in about 50% of breast cancers relative to normal breast tissue from the same patients." (PMID 21209903, 2010). "Therefore, the expression profiles of six2, CYP4Z1, and CYP4Z2P can predict chemotherapy sensitivity in patients with breast cancer." (PMID 41431719, 2026). "Furthermore, it is demonstrated that six2 can increase the expression of CYP4Z1 and CYP4Z2P and also activate ceRNET_CC by binding to their promoters, which in turn promotes the stemness of breast cancer cells." (PMID 41431719, 2026). "The authors further confirmed that the ceRNET formed between CYP4Z1 and the pseudogene CYP4Z2P serves as a sub-ceRNET specifically dedicated to hTERT, as it competitively binds to miR-125a-3p, consequently inhibiting apoptosis in breast cancer cells." (PMID 37612721, 2023). "CYP4Z1 was abnormally translocated at breast cancer cell membranes and stimulated the formation of anti-CYP4Z1 autoantibodies in breast cancer patient sera in comparison with none in the control group." (PMID 36143940, 2022). "Further investigation into the mechanisms by which CYP4Z1 contributes to tumorigenesis revealed that expression of the pseudogenes CYP4Z1-3′UTRs and CYP4Z2P synergistically increased tumor angiogenesis in breast cancer partly via the activation of the PI3K/Akt and ERK1/2 pathways." (PMID 36143940, 2022). "Interestingly, among DEGs, a relevant number of genes involved in oxidative metabolism (e.g. GSTP1, CYP4Z1, AKR1B10) and in different pathways affecting breast cancer behavior (WNT5A), was observed." (PMID 33863935, 2021). "High CYP4Z1 expression was displayed in the positive control breast cancer tissue, while no expression was observed in the negative control." (PMID 34590601, 2021). "Further analysis of the mechanistic role of CYP4Z1 in the tumourigenesis process showed that synergic expression of pseudogene CYP4Z2P and CYP4Z1-3’UTRs enhanced tumour neovascularization in breast cancer partly through activating pathways of PI3K/Akt and ERK1/2." (PMID 34590601, 2021).